CRP (C-reactive protein)
Diseases named in the same sentence as CRP in open-access papers (continued):
Sharing a sentence is not in itself a finding about the gene and the disease.
malaria (continued). "We excluded the infants whose mothers had HIV, malaria, or helminth infections but we did not test for other diseases which could induce inflammation in the infants and might affect the CRP concentration in the infants and their mothers." (PMID 24708690, 2014). "As is known from studies in patients with severe malaria, co-infections may occur frequently in patients with malaria, which in itself may lead to a rise in CRP levels, irrespective of the malaria disease severity." (PMID 22221299, 2012). "The laboratory results of travellers with severe malaria were further characterized by significantly lower platelet counts and haemoglobin levels and by significantly higher plasma lactate, bilirubin and CRP levels compared to patients with non-severe P. falciparum malaria." (PMID 22221299, 2012). "Our study suggests that in in-hospital children without WHO criteria for parenteral antibiotics, elevated levels of PCT or CRP in absence of malaria parasites could indicate the need of antibiotics." (PMID 20976241, 2010). "In children with low CRP levels, lack of such protection may permit a lack of clearance of debris and a progression from uncomplicated to severe malaria." (PMID 18312656, 2008). "in 2020 in the BMJ Global Health Journal, with the pooled estimate being that CRP predicted malaria and bacterial infection with equal efficacy, but could not distinguish between both, and CRP was at least as effective as other common biomarkers like PCT, WBC count and ANC count in doing so." (PMID 37478118, 2023). "However, in children with malaria, CRP levels were not significantly higher during bacterial than viral pneumonia (median 217.4 vs. 96.8 mg/l, p = 0.052), indicating that CRP might be valuable as a diagnostic only after malaria has been ruled out." (PMID 27486746, 2016). "At these cut-offs, CRP had a Positive Predictive Value (PPV) of 68.75% and 85.00% for malaria and bacterial infection respectively, with a Negative Predictive Value (NPV) of 94.74% and 89.05% respectively." (PMID 37478118, 2023). "But of those who were tested negative for malaria by RDT, 35.5% (44/124) also had a negative CRP test." (PMID 36536340, 2022). "Like in the IMS, the accuracy of CRP and PCT was lower in patients with malaria compared to those without." (PMID 33647009, 2021). "Unger and colleagues demonstrated that malaria-negative women with high levels of sEng, CRP, and sFlt-1 were more likely to deliver PTB, which they attributed to other inflammatory stimuli, including infections other than malaria." (PMID 31574087, 2019). "Our study sample was restricted to participants with no missing values for RBP, CRP, AGP, or malaria (in surveys that measured malaria)." (PMID 28615251, 2017). "A multivariate analysis of ln ferritin with both ln CRP and ln AGP in the model generally dampened the ln-CRP slope and ln-AGP slope in PSC and WRA as did the inclusion of malaria (data not shown)." (PMID 28615259, 2017). "Our study sample was restricted to participants with no missing values for ferritin, sTfR, CRP, AGP, or malaria (in countries that measured malaria), which resulted in a total of 8413 PSC and 4258 WRA observations." (PMID 28615255, 2017). "When individuals were stratified by malaria status and by 4-inflammation levels, geometric mean RBP concentrations tended to be lower in the PSC group with malaria and elevated CRP and AGP concentrations, whereas this was not the case for women." (PMID 28615251, 2017). "Further analyses were performed in absence of P. falciparum due to the observed effect of malaria parasites in PCT and CRP levels." (PMID 20976241, 2010). "In these 13 children, CRP, s-TREM-1, CD163 and HMGB1 were higher than in those negative for malaria parasites, but these differences were not significant." (PMID 19675669, 2009).
malaria (continued). "It is hypothesized in this present study that children with malaria in Buea, Cameroon, will show elevated levels of CRP, AGP, and serum IgG4 compared to non-infected children, with a positive correlation between malaria severity and these biomarkers." (PMID 40277833, 2025). "The use of a fixed ferritin-concentration cutoff of <30 μg/L (in subjects with elevated CRP or AGP) was relatively equivalent to the IRC approach in nonmalaria settings, whereas in malaria settings, the IRC approach resulted in a greater estimated prevalence of depleted iron stores." (PMID 28615259, 2017). "Spatial analyses were conducted using a generalized linear geostatistical model with a Matern spatial correlation function and four definitions of infection status using different combinations of inflammation (C-reactive protein, CRP > 5 mg/L) and malaria parasitaemia (with or without fever)." (PMID 27391972, 2016). "In absence of malaria parasites, levels of PCT and CRP were lower in the viral group when compared to the invasive bacterial one (PCT: median = 0.21 versus 8.31 ng/ml, p<0.001; CRP: 18.3 vs. 185.35 mg/l, p<0.001)." (PMID 20976241, 2010). "C reactive protein (CRP), a marker for the presence of inflammation, has been extensively studied for distinguishing bacterial from non-bacterial infection in febrile patients, but its role in excluding malaria in the febrile child has not been thoroughly evaluated." (PMID 37478118, 2023). "The fact that both CRP and AGP normalized at least 2 weeks earlier than ferritin suggests that this practice may not be sufficient to fully compensate for the effect of malaria on ferritin." (PMID 30537973, 2018). "Additionally, in absence of malaria parasites elevated levels of PCT and CRP could warn of invasive bacterial pneumonia at peripheral health posts and outpatient departments." (PMID 20976241, 2010).
Hyponatremia (212 papers, 2003 to 2026). An abnormally decreased sodium concentration in the blood. "When combined with other inflammatory markers, such as CRP and neutrophil count, hyponatremia further enhanced risk stratification, potentially aiding in the earlier identification of high-risk cases." (PMID 40506956, 2025). "Risk factors for LZD-associated hyponatremia include high C-reactive protein (CRP), concomitant potassium-sparing diuretics administration, advanced age, low baseline serum sodium levels, and low serum albumin levels." (PMID 40542403, 2025). "Nevertheless, the study highlighted that low-cost and easily measurable parameters, such as hyponatremia, can enhance diagnostic accuracy when used alongside other inflammatory markers like CRP." (PMID 40282883, 2025). "Consistent with previous findings, significant associations between CRP levels and hyponatremia (Na+ < 135 mmol/L) have been identified, and CRP’s diagnostic utility for UTIs has been confirmed by multiple studies." (PMID 40838209, 2025). "The analysis suggests that hyponatremia was associated with elevated CRP levels and lower albumin levels, markers of inflammation." (PMID 37744432, 2023). "A younger age, male sex, and higher levels of ESR and CRP were all independent risk factors for hyponatremia." (PMID 37353742, 2023). "In a study on Kawasaki disease, elevated CRP was associated with elevated IL-6, elevated IL-1β, and subsequently rates of hyponatremia." (PMID 37744432, 2023). "After adjustment for relevant confounders, hyponatremia remained associated with an increased square root CRP (β = 1.79: 95% CI: 0.22–3.36) and lower albumin levels (β = −0.22: 95% CI: −0.42–−0.01)." (PMID 37744432, 2023). "In mutually adjusted models, CRP above ≥20 mg/l and severe hyponatraemia (Na < 125 mM/l) were associated with increased delirium severity." (PMID 36856697, 2023). "Both hyponatremia and elevated CRP levels have been linked to renal parenchymal inflammation during acute pyelonephritis." (PMID 37587378, 2023). "Previous studies have shown a correlation between gammagraphic abnormalities and hyponatremia and an association between lower serum sodium concentration, higher CRP levels, and more severe illness in UTI patients." (PMID 37587378, 2023). "In hyponatremia, young age and high CRP levels showed significant associations with TB diagnosis (p<0.0001)." (PMID 36227934, 2022). "Adding to that, CRP, an end-product of the IL-6 inflammatory pathway, was tied with an increased risk of hyponatremia." (PMID 36714113, 2022). "Clinically, a workup including blood cell count and CRP can direct the search for the cause of hyponatremia towards infections and lead to consideration of TB, whilst a higher disease burden warrants increased diagnostic efforts." (PMID 36227934, 2022). "It has also been reported that CRP, IL-6, IL-1β, and neutrophil counts are associated with hyponatremia." (PMID 35356251, 2022). "Young age and high CRP parameters conferred a higher TB diagnosis risk in patients with hyponatremia in a multiple logistic regression model for correlated data." (PMID 36227934, 2022). "High percentages of neutrophils in white blood cells, high ALT and CRP levels, hyponatremia, and days after fever onset were associated with ineffectiveness of IVIG in univariable analysis." (PMID 34499692, 2021). "Hyponatremia was associated with the highest levels of CRP, NT-proBNP (marker of neurohormonal activation), GGT, alkaline phosphatase and eGFR and the lowest levels of FEV1." (PMID 26298426, 2016). "The increased risk of total mortality in men with hyponatremia was to some extent associated with muscle mass, CRP, alkaline phosphatase and NT-proBNP." (PMID 26298426, 2016). "Multiple logistic regression analysis showed that increased CRP level (OR 1.480, p = 0.023) was an independent risk factor for the development of hyponatremia in combined cohorts of children and adults with SLE." (PMID 27193532, 2016).
Hyponatremia (continued). "Hyponatremia remained independently associated with adverse outcomes after adjusting for age, lack of medical co-morbidities, vaccination status, year of admission, CRP, LDH, and ferritin." (PMID 39204294, 2024). "There was a significant association between hyponatremia and higher CRP and lower serum albumin levels which may suggest increased inflammation in children with hyponatremia and COVID19/MISC." (PMID 37744432, 2023). "Hyponatremia was associated with a lower albumin and higher square root CRP levels." (PMID 37744432, 2023). "Adjusted models associations of hyponatremia with CRP and albuminc." (PMID 37744432, 2023). "Yet hyponatremia was associated with a higher serum CRP and lower serum albumin, which may reflect increased state of inflammation." (PMID 37744432, 2023). "Also, it underlines the importance of an increased CRP level, hyponatremia, and high Tzanakis score as predictors for a PA." (PMID 34222491, 2021). "There have been studies that hyponatremia is associated with CRP in various diseases." (PMID 30405154, 2018). "In multivariate analyses, an older age at admission (OR 1.007, 95% CI 1.002–1.012, p = 0.006), male gender (OR 1.361, 95% CI 1.105–1.675, p = 0.004), and increased CRP levels (OR 1.093, 95% CI 1.060–1.128, P < 0.0001) were independent risk factors for the development of hyponatremia." (PMID 30405154, 2018). "Inotrope use was an independent predictor of post-discharge 1-month mortality with a HRadjusted of 1.839 (95% CI 1.227–2.757, p = 0.003), while old age, hyponatremia, renal replacement therapy during admission, high uric acid, and high c-reactive protein were the associated independent predictors." (PMID 30340408, 2018). "Similarly to these three parameters; hyponatremia, CRP, and AKI; the detected association with mild pelviectasis may reflect inflammation of the kidney parenchyma." (PMID 37587378, 2023). "Furthermore, blood tests revealed leucopenia with associated lymphocytosis and increased mononuclear cells, hyponatremia (129 mEq/L), decreased estimated glomerular filtration rate (eGRF) with increased plasma urea (99 mg/dL), and a rise in C-reactive protein (CRP) (42.75 mg/dL)." (PMID 34827385, 2021). "Furthermore, we are the first to demonstrate, using multiple logistic regression analyses, that among children hospitalized with various respiratory tract infections, an older age, being male, coinfection, and increased CRP levels are independent risk factors for the development of hyponatremia." (PMID 30405154, 2018). "Laboratory evaluation revealed hyponatremia (132 mmol/L) and markedly elevated inflammatory markers (CRP 480 mg/L, procalcitonin 41 ng/mL)." (PMID 42186615, 2026). "The patient presented with vomiting, diarrhea, and anorexia, with laboratory findings of hyponatremia, hypokalemia, and increased CRP as well as moderate elevation in ALP and BUN levels." (PMID 40284857, 2025). "Initial blood tests revealed a mild elevation of C-reactive protein (CRP 1.0 mg/dL), hyponatremia (Na 125 mEq/L), and a markedly elevated creatine kinase (CK 3000 U/L)." (PMID 41394839, 2025). "Elevated inflammatory markers, such as CRP and urea, were frequent findings, and electrolyte imbalances, particularly hyponatremia, were observed in approximately 20% of cases." (PMID 40065896, 2025). "When hyponatremia is considered alongside other inflammatory markers, such as CRP and neutrophil count, the predictive value for ACA is enhanced further." (PMID 40506956, 2025). "Laboratory investigations revealed mild hyponatremia and a markedly elevated C-reactive protein (CRP) level of 149 mg/L (normal range: <6 mg/L), suggesting an underlying inflammatory process." (PMID 40041645, 2025). "His C-reactive protein also dropped to 115.40 mg/L, and his hyponatremia was corrected with aggressive fluid resuscitation." (PMID 40821270, 2025).
Hyponatremia (continued). "The most common laboratory abnormalities were as follows: electrolyte disturbances (75%; n = 90; including hyponatremia in n = 59 and hypokalemia in n = 45 patients), elevated CRP concentration (51.7%; n = 62) and hypertransaminasemia (44.2%; n = 53)." (PMID 41374991, 2025). "Further investigations demonstrated severe hyponatraemia, elevated C-reactive protein and left basal consolidation on chest X-ray." (PMID 41458663, 2025). "Patients with hyponatremia had a median C-reactive protein (CRP) level of 15.71 mg/dL (7.62–25.67 mg/dL)." (PMID 39451561, 2024). "Laboratory data on admission revealed normal white blood cells (7010/μL, 82% neutrophils, 7% lymphocytes), hematocrit 36.9%, hyponatremia (sodium (Na) 132 mmol/L), and elevated C-reactive protein (CRP) levels (25.22 mg/dL) and procalcitonin (2.56 ng/mL)." (PMID 39720376, 2024). "At the admission, a significant increase of C-reactive protein (CRP) and hyponatraemia was found in 100% of cases." (PMID 36959663, 2023). "Assessments of serum electrolyte levels suggested hyponatremia (133.5 mmol/L) and hypokalemia (3.45 mmol/L), and the levels of inflammatory markers (C-reactive protein (CRP), procalcitonin, and IL-6) were slightly elevated." (PMID 37723545, 2023). "Biochemical examinations showed leukocytosis (12.30 × 103/mL, neutrophils 9.59 × 103/mL), further increased CRP (8.71 mg/dL), thrombocytosis (platelet = 450 × 103/mL), and hyponatremia (Na 130 mmol/L), in addition, NT-proBNP 1223 pg/mL and troponin T 13 ng/L." (PMID 36900053, 2023). "PICU patients had higher prevalence of hyponatremia, elevated admission CRP levels, and elevated D-dimer; they also had lower albumin, potassium, calcium, sodium, and platelet count." (PMID 37744432, 2023). "Using bivariate analysis, the admission clinical and laboratory features associated with greater LOS were symptom duration (fever and GI symptoms), immature neutrophils, elevated CRP, and hyponatremia." (PMID 35463908, 2022). "Relevant laboratory tests indicated type I respiratory failure, hyponatremia, pancytopenia, hypoproteinemia, elevated C-reactive protein (CRP), increased ferritin, and slightly elevated D-dimer, total bilirubin and glucose." (PMID 35197012, 2022). "Laboratory tests: normal blood count, renal and hepatic function preserved, hyponatremia, elevated D-dimer, CRP, troponins and proBNP; Ig G serology for SARS CoV-2 positive." (PMID 36096831, 2022). "The strongest predictors were hyponatremia < 133 mmol/L, elevated CRP > 187 mg/L and elevated LDH > 225 mmol/L (AUC respectively 0.71, 0.75 and 0.81)." (PMID 35534798, 2022). "The groups were clinical and laboratory similar, except for older age, presence of skin rash, previous antibiotic use, hyponatremia and increase in C-reactive protein (CRP) which were more frequent in the group 1." (PMID 36096831, 2022). "An increased CRP level and Tzanakis score, together with hyponatremia, were of independent predictive value for a PA." (PMID 34222491, 2021). "Analysis of laboratory parameters for SARS‐CoV‐2 detectable and SARS‐CoV‐2 non‐detectable cohorts revealed hyponatremia, eosinopaenia, and raised C‐reactive protein (CRP) as predictive markers for SARS‐CoV‐2 positivity." (PMID 33768594, 2021). "The laboratory studies showed elevated inflammatory markers (157 mg/L C-reactive protein, CRP, normal value < 5 mg/l), and a severe hyponatremia of 107 mmol/l (normal value between 135–145 mmol/l)." (PMID 34689748, 2021). "Monocytes counts and CRP levels were significantly elevated in subgroups with low serum sodium (hyponatremia or Q1) as compared with other sodium subgroups." (PMID 33552948, 2020). "Laboratory studies indicative of severe disease include hyponatremia, elevations in d-dimer and C-reactive protein levels, increased ferritin, and evidence of myocardial injury or multiple organ dysfunction syndrome." (PMID 33217259, 2020).